SLC1A5 (solute carrier family 1 member 5)
Diseases named in the same sentence as SLC1A5 in open-access papers (continued):
Sharing a sentence is not in itself a finding about the gene and the disease.
tumor (continued). "IHC assay demonstrated that the protein levels of SLC1A5, Ki67 and MMP9 in tumor tissues were suppressed by the silence of circ-SFMBT2, indicating that circ-SFMBT2 could promote tumor proliferation and metastasis in mice." (PMID 34530825, 2021). "Under the cutoff value of p < 0.05, no tumor showed significantly lower SLC1A5 expression than its corresponding normal tissue." (PMID 34367941, 2021). "Also, SLC1A5 expression showed strong correlations with diverse immune marker sets in HCC and LGG, indicating its role in regulating tumor immunity." (PMID 34367941, 2021). "Manipulating such therapies to increase SLC1A5, SLC3A2, and SLC7A5 expression in the immune cells could enhance anti-tumor immunotherapy and lead to developments in the field." (PMID 33953707, 2021). "Although SLC1A5 has not been well investigated for its role in tumor immunity, it is known that SLC1A5 is required in Th1 and T helper-cell 17 (Th17) induction and is a major regulator of glutamine transport in T lymphocytes." (PMID 34367941, 2021). "Solute carrier family 1 member 5 (SLC1A5) is reported to be a driver gene of ferroptosis that mediates the uptake of glutamine, a conditionally essential amino acid in rapidly proliferating tumor cells." (PMID 34568075, 2021). "Solute carrier family 1 member 5 (SLC1A5) and solute carrier family 7 member 5 (SLC7A5) are two key amino acid transporters that have been attracting attention due to their role in supporting tumour metabolism." (PMID 31819174, 2020). "Additionally, IDO-1 expressing tumor cells respond to tryptophan shortage by expressing amino acid transporter genes (i.e., SLC7A11, SLC1A4, and SLC1A5)." (PMID 33330446, 2020). "Consequently, SLC1A5 undergoes ubiquitination and degradation, leading to impaired glucose uptake, decreased mTOR activity and retarded TNBC tumor growth." (PMID 32296646, 2020). "Neutral amino acid transporter B (SLC1-A5) is an important glutamine transporter in the regulation of essential amino acid influx; and importantly, depletion of SLC1-A5 is demonstrated to abolish tumor progression." (PMID 32855630, 2020). "Our study revealed that SLC1A5 protein expression was significantly higher in adenocarcinomas with lymph node metastases at diagnosis compared to node negative tumors, indicating more aggressive tumor behavior upon higher SLC1A5 expression." (PMID 31668020, 2019). "GLUT1 and SLC1A5 expression correlate with aggressive tumor behavior in adenocarcinomas but not in squamous cell NSCLCs." (PMID 31668020, 2019). "Functional coupling of SLC1A5 and SLC7A5 was observed in HeLa cells by transport and efflux of extracellular glutamine as a substrate for leucine uptake and mTOR activation, which are important for tumor cell growth." (PMID 29562706, 2018). "The result indicated that expression of SLC1A5 in tumor tissues was significantly higher than adjacent non-cancerous tissues (P<0.0001)." (PMID 29100325, 2017). "We further analyzed the expression levels of SLC1A5 in both GC tumor specimens and adjacent non-cancerous tissues." (PMID 29100325, 2017). "Interestingly, the functional coupling of SLC1A5 and SLC7A5 glutamine transporters suggests that enhanced glutamine metabolism in tumor cells can contribute to drive tumor growth through activation of mTOR." (PMID 28040803, 2016). "In CRC, tryptophan (Trp) transporters (SLC7A5, SLC1A5) and key components of the kynurenine (Kyn) metabolic pathway (TDO2, IDO1, AFMID) are significantly upregulated, a molecular adaptation that enhances Trp uptake and catabolism to fuel tumor cell proliferation." (PMID 41488637, 2025). "Notably, SLC1A5 was restricted to tumour cells, with no expression in hepatocytes or bile duct epithelium." (PMID 40660426, 2025). "However, the negative correlation between MYC and SLC1A5 expression was significant only for luminal A tumours (P = 0.01) and not for the other subtypes (P > 0.05)." (PMID 39843491, 2025).
tumor (continued). "Besides, high SLC1A5 expression is correlated with the WHO grade and tumor size of GBM patients." (PMID 38410123, 2024). "In addition, we discovered that SLC1A5 was up-regulated in HBV-related HCC patients, and was negatively correlated with overall survival and disease-specific survival, and positively correlated with tumor progression." (PMID 36902506, 2023). "However, the relationship between SLC1A5, which is involved in immune regulation, and immune cell infiltration in the tumor microenvironment has not been elucidated, and the relationship between SLC1A5 and ferroptosis is rarely reported." (PMID 37566748, 2023). "Therefore, the functional complementarity between SLC1A5 and SLC38A1 is intertwined, and targeting both SLC1A5 and SLC38A1 could be further evaluated for their tumor suppression capability." (PMID 36262284, 2022). "However, the roles of SLC1A5 and SLC38A1 in different tumor types are still under debate." (PMID 36262284, 2022). "In addition, SLC1A5 expression was positively correlated with the number of tumor-infiltrating B cells, CD4+ T cells, CD8+ T cells, macrophages, neutrophils, and dendritic cells in HCC and low-grade glioma (LGG), indicating its role in regulating tumor immunity." (PMID 36902385, 2023). "Moreover, it has been reported that inhibiting SLC1A5 can promote the degradation of epidermal growth factor through the UPS pathway and reduce the expression of epidermal growth factor in the nucleus to help improve the sensitivity of drugs to tumor treatment." (PMID 37190313, 2023). "In particular, the amino acid transporters SLC1A5 and SLC7A5 as well as the ancillary subunit SLC3A2, which are required for efficient uptake of glutamine and leucine respectively, could strengthen the metabolic capabilities and effector functions of tumor-directed CAR-NK and T cells." (PMID 33953707, 2021). "Interestingly, other studies have shown that SLC1A5 suppression or deletion fails to prevent tumor growth, but this discrepancy could be due to the effect of the mitochondrial variant of SLC1A5, which was previously overlooked." (PMID 33953707, 2021). "SLC1A5/ASCT2 is the primary Na+-dependent glutamine transporter, whose expression is significantly higher in HCC tumor tissues compared to adjacent non-tumor tissues, and positively correlated with tumor size, making it a potential prognostic indicator." (PMID 41293169, 2025). "The glutamate transporter ASCT2, also recognized as SLC1A5, a neutral amino acid transporter in the SLC1 family, is notably elevated in various tumor types compared to regular tissues." (PMID 40860678, 2025). "In contrast, although SLC1A5 and SLC38A2 showed statistically significant differences in certain datasets, their expression levels between normal intestinal epithelium and tumour cells were not markedly distinct." (PMID 40660426, 2025). "Blocking SLC1A5 using the small molecule inhibitor GPNA inhibited Gln uptake and subsequent tumor growth in basal-like TNBC but not in luminal A tumours using MCF-7 cells as an in vitro model." (PMID 39843491, 2025). "SLC1A5 expression in both LGG and HCC showed significantly negative correlations with their tumor purities, indicating its comparative expression in the TME." (PMID 34367941, 2021). "Low proliferative, but not high proliferative, luminal tumours also showed a weak positive correlation between GLS2 protein and c-MYC (p < 0.001), SLC1A5 (p < 0.05) and SLC3A2 (p < 0.001)." (PMID 34439127, 2021). "However, the lack of SLC1A5 is not accompanied by tumor cells' growth inhibition but leads to amino acid starvation and SLC38A1 upregulation as a functional replacement for SLC1A5." (PMID 38705513, 2024).
infection (20 papers, 2015 to 2025). The state of being infected such as from the introduction of a foreign agent such as serum, vaccine, antigenic substance or organism. "In contrast, the increased Gln uptake in TRIM6-deficient cells was significantly inhibited by SLC1A5-KD infection." (PMID 36654781, 2023). "The knockdown of SLC1A5 not only inhibited the increase in intracellular glutamine levels induced by PoRVA infection, but also eliminated the effect of PoRVA infection on PEDV replication." (PMID 38905309, 2024). "Further studies showed that PoRVA infection promoted glutamine uptake by upregulating the expression of the glutamine transporter protein SLC1A5." (PMID 38905309, 2024). "Collectively, these results suggest that PoRVA G9P infection leads to a more significant increase in SLC1A5 expression than G5P infection, which is critical for the uptake of glutamine and the promotion of PEDV infection." (PMID 38905309, 2024). "PoRVA infection induces increased expression levels of SLC1A5, GLS1, and GLUD1, which enhance glutamine uptake, TCA cycle flux, and ATP production." (PMID 38905309, 2024). "We examined the expression of glutamine transporter proteins in PoRVA-infected intestinal epithelial cells and determined that PoRVA infection increases glutamine uptake primarily through the upregulation of SLC1A5/ASCT2 expression." (PMID 38905309, 2024). "In support of the activation of glutamine metabolism in response to infection, we detected a significant induction of genes involved in glutamine import and utilization, such as Gls and Slc1a5, in the lungs of mice after A. fumigatus infection." (PMID 36475892, 2023). "Infection of human monocytes by F. tularensis LVS also triggered the deglycosylation of the glycosylated amino acid transporter SLC1A5 and other glycoproteins." (PMID 28377902, 2017). "We previously showed that human monocyte infection by F. tularensis LVS triggered deglycosylation of the glutamine transporter SLC1A5." (PMID 28377902, 2017). "Involvement of a eukaryotic glutamine transporter SLC1A5 has been recently described during F. tularensis LVS infection." (PMID 25705612, 2015). "This deglycosylation process increases with the time of infection and is correlated with the increase in SLC1A5 expression." (PMID 25705612, 2015). "Notably, RVA-HNNY infection more markedly promoted SLC1A5, GLS1 and GLUD1 expression to more significantly increase the uptake and catabolism of glutamine than RVA-SXXA infection." (PMID 38905309, 2024). "The differential effect of F. tularensis LVS infection on SLC1A5/SLC7A5 expression could therefore induce an increase in intracellular concentration of glutamine." (PMID 25705612, 2015). "In SLC1A5-/- IPEC-J2 cells, the effect of PoRVA infection on the subsequent PEDV infection-induced increase in cellular ATP levels disappeared." (PMID 38905309, 2024). "The mRNA level of SLC1A5, GLS1, and GDH increased significantly at 6 h post infection (p.i.)compared to oncoVV in PLC/PRF/5." (PMID 39057416, 2024). "We harvested cells at 6, 12, and 18 h after PoRVA infection (RVA-HNNY and RVA-SXXA) to further investigate the expression of SLC1A5 during PoRVA infection." (PMID 38905309, 2024). "PoRVA infection increased the mRNA levels of SLC1A5 and SLC38A1, but did not affect the mRNA levels of other glutamine transporters." (PMID 38905309, 2024). "As expected, neither RVA-HNNY infection nor RVA-SXXA infection was effectively increased the PEDV titer or viral yield in SLC1A5-/- IPEC-J2 cells." (PMID 38905309, 2024). "In SLC1A5-/- IPEC-J2 cells, PoRVA infection did not increase the intracellular glutamine concentration." (PMID 38905309, 2024). "The infection rate of the reporter virus was significantly decreased in KO cell lines devoid of CD147 (HEK293T ΔCD147 cl1 and HEK293T ΔCD147-SLC1A5 cl2) but relatively unimpaired in cells lacking SLC1A5 (HEK293T ΔSLC1A5 cl1)." (PMID 33717005, 2021).
adenocarcinoma (4 papers, 2018 to 2025). A common cancer characterized by the presence of malignant glandular cells. "Furthermore, SLC1A5 protein expression was significantly higher in adenocarcinomas with worse pTNM stage (r(s) = 0.39, P = 0.009)." (PMID 31668020, 2019). "Furthermore, SLC1A5 protein expression was significantly higher in adenocarcinomas with lymph node metastases compared to node negative tumors (r(s) = 0.34, P = 0.028) and in adenocarcinomas with higher pTNM stage (r(s) = 0.39, P = 0.009)." (PMID 31668020, 2019).
cardiovascular disease (3 papers, 2023 to 2024). "Prior research has established a link between SLC1A5 and cardiovascular disease." (PMID 39695878, 2024).
SLC1A5 also shares sentences with these, for which no sentence is quoted: tongue cancer (5 papers); brain tumor (4); diabetes (4); multiple myeloma (4); neurological diseases (4); astrocytoma (3); cervical cancer (3); heart failure (3); lymphoma (3); oral squamous cell carcinoma (3); preeclampsia (3); prostate tumors (3); cystinuria (2); laryngeal squamous cell carcinoma (2); mood disorder (2); acute monocytic leukemia (1); adenovirus infection (1); adrenal pheochromocytoma (1); amyotrophic lateral sclerosis (1); anemia (1); bacterial infection (1); basal-like breast carcinoma (1); benign prostatic hyperplasia (1); bladder cancer (1); brain cancer (1); cardiac hypertrophy (1); Cirrhosis (1); Colon (1); colorectal adenocarcinoma (1); depression (1).
A further 37 diseases each share a sentence with SLC1A5 in 1 paper.